IL4 (interleukin 4)
Diseases named in the same sentence as IL4 in open-access papers (continued):
Sharing a sentence is not in itself a finding about the gene and the disease.
Obesity (continued). "However, the effect of anti-inflammatory cytokines, such as IL-4, in the development of insulin resistance or obesity is less understood." (PMID 24347527, 2014). "The M2 macrophages are alternatively activated by interleukin-4 (IL-4) stimulation and the peroxisome proliferator-activated receptor gamma (PPARγ) receptor and have been demonstrated to protect against the metabolic consequences of obesity in mice." (PMID 23844276, 2013). "Interestingly, an in vivo mouse study reported that IL-6 secretion from adipocytes derived from donors with obesity could stimulate adipose tissue macrophages, leading to IL-4 signaling and contributing to an anti-inflammatory environment." (PMID 40395977, 2025). "Since the majority of studies investigating the effect of EOS and IL-4 on metabolism have thus far been conducted in animals, there is currently a broad knowledge gap in the translation of these findings into the study of human disease states such as obesity and IR." (PMID 38206766, 2024). "Similarly, the administration of IL-4 increased the in situ proliferation of ATMs in lean mice, suggesting that IL-4 could play role in driving the local proliferation of ATMs in obesity." (PMID 36359228, 2022). "In conclusion, obesity-associated immunometabolic factors including LDL-cholesterol, FABP4, and leptin were associated with a higher iNKT cell IFN-γ response across all disease groups, while HDL-cholesterol and insulin sensitivity (QUICKI) were associated with a higher IL-4 response." (PMID 34635725, 2021). "Our new insights demonstrating the impact of IL-4Rα expression to high fructose-driven obesity development provide the opportunity for greater examination of IL-4 axis and the downstream linked non-canonical pathways to high-fat + high carbohydrate diets-associated metabolic disease pathogenesis." (PMID 34302121, 2021). "It is suggested that the level of IL-4 could influence obesity and overweight." (PMID 32744314, 2020). "Thus, IL-4 could be a metabolic regulator and antiobesity candidate for the treatment of obesity and its complications." (PMID 32585823, 2020). "However, in obesity, the decline in adipose tissue eosinophils in mice might promote a pro-inflammatory macrophage predominance due to less eosinophil-derived IL-4 and IL-10." (PMID 29479350, 2018). "Other common genetic variants like the IL-1β promoter region and exon-5 and IL4 -590 T/C single nucleotide polymorphisms, which were not screened in this study, could have association with obesity and its related parameters." (PMID 28293435, 2017). "These suggest that IL-4 may participate in the processes of diet-induced obesity and metabolism." (PMID 28293435, 2017). "Importantly, a significant reduction in the in situ proliferation of ATMs was observed in the HFD-treated STAT6-deficient mice as compared with that of wild-type mice, demonstrating an important role of IL-4 in driving the local proliferation of ATMs in obesity." (PMID 27031964, 2016). "Thus the IL-4/STAT6 signaling is the driving force for ATM proliferation in obesity." (PMID 27031964, 2016). "Additionally, it was observed that both the reduction of temperature and the IL4 might have a protective metabolic effect from obesity." (PMID 26339249, 2015). "It has been demonstrated that IL4 was able to improve insulin sensitivity and glucose tolerance in an animal model of diet induced obesity, therefore its up-regulation could be a tentative to restore insulin sensitivity, which is a common pathogenetic mechanism in DM and NASH." (PMID 26599575, 2015). "Given the protective role of IL-4 in metabolic regulation we speculate, that in the absence of NKT cells this protection is lost, thus lending NKT cell-deficient mice more susceptible to HFD-induced obesity and metabolic dysfunction." (PMID 24465369, 2014).
Obesity (continued). "Interestingly, adoptive transfer of CD4+ cells especially Th2 CD4+ T cells, which produce IL-4 and IL-13, rescues HFD-induced obesity and insulin resistance in Rag1 deficient mice suggesting that Th2 cytokines such as IL-4 and IL-13 suppress HFD-induced inflammation to improve insulin sensitivity." (PMID 23781214, 2013). "Basal cytokine production (IFN-γ, TNF-α, IL-4) was also significantly and specifically increased in CD4− (CD8+) iNKT cells from individuals with obesity compared to lean individuals." (PMID 41000378, 2025). "However, in mice with obesity induced by genetic deficiency in carboxypeptidase E (Cpefat model), sensitized and challenged with OVA, levels of chemerin in BAL fluid and other markers, including IL-4 or IL-13, were significantly higher compared to wild-type counterparts." (PMID 38542187, 2024). "We analyzed AT from individuals with obesity and age-matched lean counterparts for AT-EOS content, IL-4, circulating leptin levels, and measures of IR." (PMID 38206766, 2024). "The role of IL-4 and interferon- γ (IFN-γ) in obesity-related epithelial remodeling should be considered." (PMID 38562155, 2024). "Regarding the correlation analyses of RAS components with hepatic cytokines in individuals with obesity and MASLD, a significant positive correlation was observed between ACE, and all analyzed cytokines (TNF-α, IL-6, IL-4, IL-13, IL-10)." (PMID 39337863, 2024). "Based on these data, we propose that, during obesity, reduced AT-EOS content is accompanied by decreased IL-4 levels, and this adversely affects adipocyte leptin secretion, thereby contributing to development of hyperleptinemia and leptin resistance." (PMID 38206766, 2024). "In the present study, we report that individuals with obesity, IR, and hyperleptinemia presented with a marked reduction in AT-EOS content accompanied by decreased levels of local and systemic IL-4." (PMID 38206766, 2024). "Combined with our assessment of the inflammatory status of our cohorts, these data suggest that, as previously identified in an animal model of diet-induced obesity, there is a close connection between AT-EOS, IL-4, inflammation, and IR in humans." (PMID 38206766, 2024). "Effect modification by overweight/obesity was significant in 3 of the proteins in the sex‐adjusted model: fibroblast growth factor 21 (FGF21), interleukin 4 (IL‐4), and uPA." (PMID 36973952, 2023). "Finally, we performed a gene correlation analysis of IL13 and IL4 expression with cytokine receptors, fibrosis markers, IL-13/IL-4 signaling components, and metabolic parameters in human WAT to address the clinical relevance of our data and potential association with parameters of obesity." (PMID 36982747, 2023). "Inflammatory biomarkers including hs‐CRP, IL‐6, IL‐4, IL‐1B, IL‐10, and TNF‐α have also been shown to be connected with obesity, diabetes, and CVD." (PMID 36911829, 2023). "At time 0, the level of transcription (mRNA) of all genes analyzed were higher in the group with obesity compared with the control group, ranging between 3.5-times of TNF-α and 18.7-times of IL-4." (PMID 37215211, 2023). "DEGs in the CDs significantly affected biologically related functions and signaling pathways such as IL-4 Signaling Pathway, RUNX3 Regulates Notch Signaling, IL-1 and Megakaryocytes in Obesity Pathway, and Overview of Leukocyteintrinsic Hippo Pathway." (PMID 37274215, 2023). "Similar to our findings in peripheral blood, AT-resident iNKT cells produce IL-4 under lean conditions, but IFN-γ during obesity, which contributes to adipose tissue inflammation and the development of insulin resistance." (PMID 34635725, 2021). "After observing the upregulation of microglial IL4Ra in early obesity and a requirement for IL4 in synaptic rescue after SAT transplantation, we investigated potential sources of IL4 in the CNS and periphery." (PMID 34330904, 2021).
Obesity (continued). "In obesity, a decrease in cell populations, such as ILC2s and eosinophils in VAT leads to insufficient production of IL-4." (PMID 34421909, 2021). "Fas mutant mice show a lean phenotype and prevent HFD-induced obesity by upregulating the expression levels of UCP1, IL-4, and IL-10 in WAT." (PMID 34576181, 2021). "SLKDT intervention significantly inhibited obesity‐induced inflammation by decreasing the proinflammatory factors IL‐6, TNF‐α, IFN‐γ, and IL‐1β and increasing the anti‐inflammatory cytokines IL‐4 and IL‐10." (PMID 32884731, 2020). "Development of obesity in mice was correlated with a change in cytokine profile with decreased IL-2 and increased IFN-γ and IL-4." (PMID 31947953, 2020). "In order to investigate the role of a broad range of pro- and anti-inflammatory cytokines in obesity, serum levels of TNF-α, IFN-γ, IL-2, IL-4, IL-5, IL-10, IL-12, IL-13, and GM-CSF were compared between obese and non-obese participants." (PMID 25781614, 2015). "Further, a recent study demonstrated that IL-4 produced by eosinophils, in the visceral adipose tissues is important in protecting mice from HFD-induced obesity, through the maintenance of alternatively activated macrophages." (PMID 24465369, 2014). "Statistically, the concentrations of GROα, IL-2, IL-4, IL-6, IL-17A, IL-22, IL-23, and MCP-3 were significantly higher in males with obesity compared to the females with obesity, while the concentrations of IL-5, IL-10, IL-18, MCP-1, and MIP2α trended higher (p ≤ 0.1)." (PMID 41488663, 2025). "Elevated anti-inflammatory cytokines (IL-4 and IL-10) and neurotrophic factors (BDNF, IGF-1) in silymarin-treated mice suggest that silymarin may offer neuroprotective benefits by mitigating obesity-related neuroinflammation." (PMID 39624169, 2024). "After infection, the results of IFN-γ, TNF-α, IL-4, IL-10 and IL-12 p70 in obesity + infection group were not obviously different from those in normal + infection group." (PMID 38185681, 2024). "Individuals with obesity and type 2 DM have significantly higher matrix metalloproteinase-9 and interleukin-4 (IL-4) expression than those without these conditions." (PMID 38343638, 2024). "This review examines the major mechanisms between obesity and AD, which focus on the effect on skin and gut microbiota, immune responses mediated by the toll like receptor (TLR) signaling pathway, and changes in cytokine levels (TNF-a, IL-6, IL-4, and IL13)." (PMID 39564133, 2024). "Individuals with obesity exhibit markedly reduced immunological tolerance, leading to excessive production of inflammatory mediators such as IL-6, TNF-α, IL-1β, and IFN-γ, alongside a significant decrease in anti-inflammatory cytokines like IL-4 and IL-10." (PMID 38840158, 2024). "During obesity, the AT-EOS content is reduced, leading to a reduction of IL-4 within AT." (PMID 38206766, 2024). "Functional analysis revealed that six MRHGs significantly affected biologically relevant functions and signaling pathways such as IL-4 Signaling Pathway, RUNX3 Regulates Notch Signaling Pathway, IL-1 and Megakaryocytes in Obesity Pathway, and Overview of Leukocyteintrinsic Hippo Pathway." (PMID 37274215, 2023). "Usually, pregnant women with obesity at pre-pregnancy or becoming obese have a lipotoxic placental environment leading to increased OS and elevated concentrations of TNF-α, IL-1, IL-1β, IL-3, IL-4 and IL-6, and IFN-γ." (PMID 37891973, 2023). "The correlations between gut microbiota (based on OTUs) and obesity related indexes (including body weight gain, percent of epididymal fat weight, the levels of TG, TC, HDL, LDL, TNF-α, IL-6, IL-10, and IL-4) were investigated using the Pearson correlation analysis." (PMID 35807812, 2022).
Obesity (continued). "After adjusting for sex, age, hypertension, blood lipid concentration, and obesity, the level of TNF-α in the case group was higher than that in the control group, following that of IL-10 and IL-4, which indicated that an increased plasma level of TNF-α was significantly associated with sarcopenia." (PMID 36160136, 2022). "Thus, pharmacologic or other approaches that could modulate macrophage activity and IL-4/IL-6 production in the adipose tissue during aging could be exploited therapeutically in the recovery of beige fat to potentially improve metabolic health, as been done in the field of obesity." (PMID 34423787, 2021). "Thus, it is plausible that novel pharmacological intervention in the IL-4/IL4Rα axis function, in both hematopoietic as well as non-hematopoietic cells, would provide novel approaches to dampen high dietary fructose-driven metabolic harm associated with obesity." (PMID 34302121, 2021). "Diminished IL-4 production in the context of obesity/T2D was also observable in iNKT cells, without reaching statistical significance." (PMID 32231670, 2020). "Unanswered questions include how the levels of type 2 inflammation, such as cytokines IL4, IL13, IL5, and adiponectin levels, both systemically but also locally in the airways, are affected in our model from the different stages of obesity and allergic inflammation." (PMID 33256137, 2020). "However, the opposite effect was reported to occur when IL4 was administered intracerebroventricularly (icv) to rats during HFD feeding, that is, exacerbation of obesity, further hypothalamic inflammation as well as leptin and insulin resistance." (PMID 30158466, 2018). "Levels of IL-12 were elevated in obesity, IFN-γ, IL-4, IL-5, IL-12 and IL-13 elevated in MetS." (PMID 25781614, 2015). "Obesity-induced epithelial remodeling may involve various factors, including HMGB1, the role of leptin, CysLTs, ORMDL3, matrikines like PGP, and cytokines such as IL-4 and IFN-γ, which may contribute to epithelial alterations." (PMID 38562155, 2024). "Interleukin 4 (IL-4) stimulated THP-1 macrophage-derived extracellular vesicles can improve the homeostasis of adipose factors, retargeting the energy metabolism of macrophages and adipocytes, thereby controlling the occurrence of cardiac metabolic tissue inflammation in obesity-related diabetes." (PMID 38720885, 2024). "Additionally, the role of matrikines like PGP and cytokines including IL-4 and IFN-γ may also contribute to epithelial alterations in obesity." (PMID 38562155, 2024). "Moreover, the levels of IL-10 (P < 0.001), IL-4 (P < 0.001), and TNF-α (P < 0.001) in the sarcopenia group were higher than those in the non-sarcopenia group after adjusting for sex, age, hypertension, blood lipid concentration, and obesity." (PMID 36160136, 2022). "A clinical study revealed that obesity was firmly connected with various proinflammatory cytokines, such as interleukins (ILs: IL-5, -10, -12, and -13), interferon-γ (IFN-γ), and tumor necrosis factor-α (TNF-α), and obese patients displayed elevated plasma levels of IL-4, -10, and -13." (PMID 35267958, 2022). "After observing beige fat-dependent increases in microglial IL4Ra expression in early obesity, and beige adipose-dependent rescue of LTP following SAT transplantation, we hypothesized that beige adipocytes might rescue LTP via the central actions of IL4." (PMID 34330904, 2021). "In addition, the IL-4/IRS2 pathway is essential for M2 activation in the steady state of VAT, whereas in obesity, hyperinsulinemia inhibits the IL-4/IRS2 pathway by reducing IRS2 expression on macrophages, which finally leads to the impairment of M2 activation." (PMID 34421909, 2021). "Obesity did not affect the production of IL-4 in C57BL/6 mice." (PMID 31923234, 2020). "The incubation with these SFA increased IL-4 levels and the methylation of Pparg, suggesting that Pparg hypermethylation could mediate the proinflammatory effects of these SFA and contribute to IR in obesity." (PMID 31615571, 2019).
Obesity (continued). "Besides, lipid contents in livers obtained from STZ-induced diabetic AdIL-4 mice (diabetes with transient IL-4 overexpression) and HFD + IL-4 mice (obesity-induced insulin resistant status with long-term IL-4 overexpression) were immunohistochemically analyzed." (PMID 30584465, 2018). "Apart from the crucial role of adipocyte- rather than macrophage-derived sPLA2-V in obesity, the Pla2g5 expression in macrophages is markedly induced by the M2-skewing Th2 cytokines IL-4 and IL-13 and the Pla2g5 ablation decreases the Th2-mediated immune responses." (PMID 29259680, 2016). "We know that Metrnl, as nerve growth factor, has a significant effect on the treatment of nervous system disorders, particularly hearing loss, Meniere's disease, but there is no definitive experimental evidence about Metrnl and IL-4 for the treatment of obesity." (PMID 26688684, 2015). "Obesity did not alter the percentages of circulating IFNγ+ CD8 T cells or IFNγ+, IL-4+, or IL-17A+ CD4 T cells in ccRCC subjects." (PMID 32469992, 2020). "Adipose tissue iNKT-cells have not been investigated with ageing, but considering that IL-4- and IL-10-producing NK1.1+iNKT-cells decline with obesity, it is possible that ageing has similar effects." (PMID 29479350, 2018). "At an early stage of obesity, while MCP-1, the pivotal monocyte chemoattractant, is not elevated, resident macrophage proliferation in situ is significantly enhanced greatly, depending on the IL-4/Stat6 pathway." (PMID 34421909, 2021). "In the context of gestational diabetes with obesity and multiple background of recurrent abortion, Th1 transcriptional factor and cytokines are upregulated while GATA3 and IL-4 (belonging to the Th2 phenotype) are not altered in diabetic mothers and their newborns." (PMID 30539027, 2018).